HGF (hepatocyte growth factor)
Diseases named in the same sentence as HGF in open-access papers (continued):
Sharing a sentence is not in itself a finding about the gene and the disease.
cancer (continued). "Although the cells were selected only based on their Met expression levels and their response to HGF/SF treatment, the high-Met cell lines were assigned to the Claudin-low subtype by the Perou group while the low-Met cell lines are either of the luminal cancer subtype or normal cells (MCF10)." (PMID 23049908, 2012). "Given that a duration period of intravenous HGF treatment during acute infection is probably within 7 days, we predict that the short-term injection of HGF will not increase a cancer risk, and clinical trials (Phase I) are now in progress with a careful focus on this issue." (PMID 22536224, 2012). "Thus, we examined whether serum HGF was a predictor of cancer death among apparently healthy Japanese living in the general community." (PMID 22672958, 2012). "Thus, the increase in the risk of cancer death associated with high HGF was not due to the presence of subclinical cancer." (PMID 22672958, 2012). "We investigated whether plasma HGF predicted cancer death among a population of Japanese adults." (PMID 22672958, 2012). "Given the cumulative evidence supporting Stat3 as a potential therapeutic target in cancer and that there are ongoing clinical trials testing Stat3 inhibitors, our group has attempted to better understand the molecular mechanisms of Stat3 activity and the role of HGF/c-met in transducing its signal." (PMID 21595927, 2011). "In addition, molecular complexes that inhibit cMet signalling may also provide a good opportunity for countering the action of HGF in cancer." (PMID 17576468, 2007). "Their downregulation, often via promoter hypermethylation, leads to excessive activation of hepatocyte growth factor/c-MET or protease-activated receptor-2/NF-κB signaling, promoting epithelial-mesenchymal transition and cancer progression." (PMID 41752136, 2026). "Following the same protocol as the immunofluorescence of cancer cells, RAW-Blue macrophages were treated with either TGFβ-1 (4.0 × 10−3 μg/mL), IL-6 (4.1 × 10−5 μg/mL), or HGF (5.97 × 10−4 μg/mL) and stained with E-cadherin, N-cadherin, and vimentin." (PMID 40227834, 2025). "Hepatocyte growth factor (HGF) has been demonstrated, for instance, to promote EMT and migration across a variety of cancer cells." (PMID 40801639, 2025). "The genes up-regulated in the cancer compartment in PNI predicted the activation of cell migration, movement of fibroblasts, outgrowth of axons and up-regulation of Hepatocyte Growth Factor (HGF)." (PMID 40075699, 2025). "Hepatocyte growth factor (HGF) is a multifunctional growth factor and is reported to have an important role in the progression of various cancers through the activation of MET, which is a specific receptor of HGF." (PMID 40299447, 2025). "Factors such as transforming growth factor-beta (TGF-β), hepatocyte growth factor (HGF), and interleukins secreted by CAFs can activate signaling pathways (e.g., PI3K/AKT, MAPK) in cancer cells, leading to enhanced glycolysis and survival." (PMID 40469185, 2025). "Aberrant activation of the HGF/c-MET axis has been shown to play a critical role in the development and progression of various human cancers and is often associated with poor clinical outcome and drug resistance." (PMID 40520181, 2025). "Specifically, binding of HGF to MET induces potent MET phosphorylation and subsequent downstream activation of AKT and MAPK signaling pathways which positively drive cancer cell proliferation." (PMID 41368576, 2025). "In this study, the differentiation of NFs into CAFs via co‐culture with cancer cells was confirmed by quantifying the mRNA expression levels of α‐SMA, FAP, FSP‐1, CSPG4, CXCL12, and HGF using qRT‐PCR." (PMID 39801758, 2025). "This matriptase-induced HGF/c-MET signaling constitutes a second wave of EGF signaling, promoting cancer cell scattering, migration, and invasion." (PMID 40361420, 2025).
cancer (continued). "Hepatocyte growth factor (HGF) regulates neurogenesis, organogenesis, and tissue remodeling during epithelial wound healing, tissue regeneration, and cancer invasion." (PMID 40799816, 2025). "MET and HGF genes can induce epithelial–mesenchymal transition (EMT) in ESCC, endowing cancer cells with stronger invasiveness and metastatic potential." (PMID 40244296, 2025). "Neutrophils also contribute to cancer progression by releasing cytokines and growth factors, such as IL-6, TNF, epidermal growth factor, hepatocyte growth factor (HGF), and platelet-derived growth factor." (PMID 40027124, 2025). "It specifically targets the HGF-c-Met and VEGF-VEGFR pathways in cancer cells and endothelial cells, exerting potent anti-angiogenic effects." (PMID 40672375, 2025). "Conversely, hGF cells showed only slight inhibition, suggesting a selective cytotoxic effect of PAM towards cancer cell lines." (PMID 39866438, 2025). "By reversing EMT induced by EGF and HGF (hepatocyte growth factor), cardiotoxin III (CTX-III), a membrane toxin derived from the venom of the Taiwan cobra (Naja naja), suppresses the migration of cancer cells." (PMID 41321380, 2025). "Since taxanes are commonly used to treat other hormonally dependent cancers, we also analyzed the link between STMN1, HGF, MET, and STMN1/MET gene expression signatures and taxane treatment response in an mBC patient cohort using the ROCplot dataset on BC." (PMID 40723207, 2025). "TAS-115, as a multi-targeted kinase inhibitor, disrupts pro-survival signaling by blocking c-MET/HGF and VEGFR2 pathways, thereby attenuating downstream PI3K/Akt/mTOR activation and diminishing the ability of cancer cells to withstand stress." (PMID 41289612, 2025). "This is achieved through the delivery of bioactive molecules like matrix metalloproteinases (MMPs) and hepatocyte growth factor (HGF), which alter the ECM and facilitate cancer cell movement." (PMID 40693234, 2025). "Recent studies have highlighted the important role of pro-inflammatory cytokines released after surgical resection, especially TGFβ-1, IL-6, and HGF, in promoting epithelial–mesenchymal transition (EMT) and enhancing cancer cell metastasis potential." (PMID 40227834, 2025). "Hepatocyte growth factor (HGF), a pleiotropic cytokine, exerts wide-ranging effects on epithelial and endothelial cell proliferation, morphogenesis, cancer progression, and inflammatory response." (PMID 40427685, 2025). "An example is the secretion of hepatocyte growth factor (HGF) by stromal cells, which can activate the MET signaling pathway, providing a survival route for cancer cells even when EGFR-targeted therapies are applied." (PMID 39861138, 2025). "This study focused on engineering an antagonistic anti-c-MET antibody capable of blocking HGF/c-MET signaling and inducing the killing of MET-overexpressing cancer cells through antibody-dependent cellular cytotoxicity (ADCC)." (PMID 39664377, 2024). "Agents that inhibit the effects of cytokines and growth factors such as TNFα, TGFβ, VEGF, and HGF, all involved in the increase of vascular permeability, decrease transepithelial/endothelial resistance and increase paracellular permeability, could be a useful tool against cancer metastasis." (PMID 39035739, 2024). "EMT programs in cancer are activated by various signaling molecules, including TGF-β, epidermal growth factor (EGF), and Hepatocyte growth factor (HGF)." (PMID 38939095, 2024). "Telisotuzumab effectively blocks both HGF-independent constitutive and HGF-dependent c-MET signaling, leading to apoptosis in cancer cells dependent on amplified c-MET signaling." (PMID 39664377, 2024). "The levels of circulating PD-L1, CXCL10, MIG, HGF, CCL-2, and IL-6 were significantly higher in the cancer group compared with those of the control group." (PMID 38776028, 2024). "Elevated circulating levels of 6 cytokines (PD-L1, CXCL10, HGF, CCL2, MIG, and IL-6) were observed in cancer patients compared with that in healthy volunteers." (PMID 38776028, 2024).
cancer (continued). "Activated CAFs secrete HGF, inducing MET activation in cancer cells, and these respond by increasing Tenascin (TNC) secretion." (PMID 38892318, 2024). "In this study, we demonstrated significantly higher levels of circulating PD-L1, CXCL10, MIG, HGF, CCL-2, and IL-6 in cancer patients compared to normal healthy subjects." (PMID 38776028, 2024). "IL-6 has also been reported to regulate cancer cell proliferation through the epidermal growth factor (EGF) and hepatocyte growth factor (HGF) families." (PMID 38510850, 2024). "Taken together, our results suggest that HAT inhibits the development of erlotinib resistance in PC9 cells by attenuating HGF production from ECs, highlighting the multifaceted action of HAT on the complex crosstalk between ECs and cancer cells." (PMID 38338342, 2024). "Key factors like Vascular Endothelial Growth Factor (VEGF) and Hepatocyte Growth Factor (HGF) play significant roles in promoting angiogenesis, making them important targets for cancer therapy." (PMID 38940900, 2024). "Human hepatocyte growth factor (HGF) is a scatter protein previously known to induce the proliferation, migration, angiogenesis, and survival of cancer cells." (PMID 38794215, 2024). "In vitro and in vivo studies have demonstrated that the HGF/MET pathway plays a crucial role in cancer growth, invasion, metastasis, and drug resistance across various cancers." (PMID 38596618, 2024). "HGF is a growth factor known to promote VM signaling pathways and induce EMT across various cancers." (PMID 38694917, 2024). "In the context of cancer, the MET oncogene contributes to tumorigenesis, metastasis, and therapeutic resistance, positioning the HGF/MET axis as a significant target for the development of novel anti-cancer therapies." (PMID 39598385, 2024). "Cancer cells secrete various growth factors (NGF and hepatocyte growth factor [HGF]), chemokines and metabolites in an autocrine and/or paracrine manner." (PMID 39119085, 2024). "Patients with advanced disease had significantly higher expression of the HGF and ANGPT2 genes compared to patients with early-stage carcinoma." (PMID 39302921, 2024). "The expression of HGF and its value in predicting survival in SCLC were explored from GEO database and in pan-cancer analysis." (PMID 37828456, 2023). "Hepatocyte growth factor (HGF), also known as scattering factor (SF) and its receptor c-Met tyrosine kinase is in charge of the proliferation of a variety of cancer cells." (PMID 37151401, 2023). "Altogether, our data suggest the presence of cytotoxic c-Met+ CD8+ clones derived from cancer patients, and these cells have a higher cytotoxic capacity compared to c-Met− CD8+ clones, which is decreased upon in vitro treatment with HGF." (PMID 38137344, 2023). "The signaling pathway of HGF/c-MET has been investigated in many solid cancer types, as it is considered an important target in the diagnosis, prognosis, and treatment of cancer." (PMID 36789987, 2023). "The insulin-like growth factor (IGF), epidermal growth factor (EGF), hepatocyte growth factor (HGF), and vascular endothelial growth factor (VEGF) are some major growth factor pathways used in trophoblast and cancer cells." (PMID 36834865, 2023). "CAFs secrete growth factors, including TGF-β, FGF2/7, PDGF, and HGF, as well as vascular endothelial growth factor (VEGF), which promote cancer cell proliferation." (PMID 36672284, 2023). "The hepatocyte growth factor (HGF), also known as scatter factor, is secreted by CAFs in some cancers." (PMID 36980785, 2023). "HGF can enhance the expression of glucose transporters GLUT1 and GLUT4 in several cancers, increasing glycolysis and nutrient consumption." (PMID 37919751, 2023). "Because of extensive preclinical research indicating a link between HGF/c-MET signaling and cancer cell survival, clinical studies targeting the c-MET axis in HNSCC have been initiated." (PMID 37373393, 2023).
cancer (continued). "The focus of our study lays on HGF as a promising prognostic marker, knowing that the HGF/MET pathway is one of the most important pro-oncogenic, pro-angiogenetic, and pro-metastatic signals in various cancer types." (PMID 37170275, 2023). "As a result, current drugs that solely target the HGF/c-MET axis and the Hh pathway demonstrate only moderate efficacy in specific types of cancer." (PMID 37919751, 2023). "The increase in paracrine HGF, which binds the c-MET receptor on the migrated cancer cells, contributes to the formation of a microenvironment that allows metastatic cancer cells to land and proliferate in liver tissue." (PMID 36834471, 2023). "HGF secreted by CAF binds to receptor tyrosine kinases to further activate the MET pathway, enhancing the crosstalk of cancer cells and hepatic stellate cells, resulting in cancer cells’ resistance to chemotherapy." (PMID 37035187, 2023). "On the other hand, CCL11 (Eotaxin), HGF, TIMP‐1 and MCP‐1 (CCL2) were secreted more by the fibroblasts compared to prostate epithelial/cancer cells." (PMID 36608258, 2023). "Mesothelial cells also support cancer cells by undergoing mesothelial-to-mesenchymal transition (MMT) induced by cytokines such as TGF-β, hepatocyte growth factor (HGF), and plasminogen activator inhibitor-1 (PAI-1) from cancer cells." (PMID 37180125, 2023). "CAFs could mediate cancer cell growth, migration and invasion depending on secreting various nutrients (lactate, glutamine) and signaling molecules, such as aspartic acid, hepatocyte growth factor (HGF), VEGF, growth arrest specific protein 6 (GAS6), and exosomes." (PMID 36945005, 2023). "Stromal cells like fibroblasts and CAFs are the main producers of HGF in the TME, and the activation of the c-Met pathway occurs in a paracrine fashion, also in cancer cells." (PMID 37686233, 2023). "For example, HGF induces the EMT program via HGFR signaling, thereby enhancing the invasive and metastatic potential of cancer cells by allowing the cells to survive in the bloodstream without anchorage." (PMID 37543570, 2023). "HGF, IL-8, and MCP-1 were shown to facilitate cancer cell migration, invasion, and metastasis by promoting EMT." (PMID 36902278, 2023). "Subtype I highly expressed hepatocyte growth factor (HGF) and fibroblast growth factor 7 (FGF7), and had strong protective effects against cancer." (PMID 36185262, 2022). "SDF-1, HGF and VEGF have been reported to promote the directional migration and invasion of human cancer cells." (PMID 35328253, 2022). "Increased activities of c-MET (mesenchymal–epithelial transition protein) and its ligand hepatocyte growth factor (HGF) promote cancer cells’ proliferation and metastasis in numerous cancers." (PMID 36233320, 2022). "We found nine eQTL, including nine eVariants and two eGenes (HGF and FCER1G), that correlated with the survival of cancer patients." (PMID 35204406, 2022). "For example, fibroblasts can release hepatocyte growth factor (HGF), which binds to MET proto-oncogene (MET) in cancer cells and provokes a continuous survival benefits." (PMID 36115852, 2022). "Subsequently, HGF activated MET-dependent signaling and enabled cancer cells to resist tyrosine kinase inhibitors." (PMID 35814444, 2022). "Regarding HGFR ́s pivotal role in cancer, the inhibition of the HGFR/HGF pathway seems to be an interesting therapeutical approach." (PMID 36359213, 2022). "CAFs are involved in the growth of HCC by producing epidermal growth factor (EGF), hepatocyte growth factor (HGF), and fibroblast growth factor (FGF), which act on adjacent cancer cells and promote rapid proliferation." (PMID 35248060, 2022). "Several lines of investigations established that stromal expression of soluble factors including HGF, TNF-α and WNT16B in the TME can promote cancer resistance to chemotherapy, radiation and targeted agents." (PMID 36202915, 2022).
cancer (continued). "Equally, altered protein levels of FLNA, HSPA7, HGF, ERO1A, and GARS1, have been related to cancer migration, adhesion, poor patient prognosis, and metastasis." (PMID 35008958, 2022). "Allogeneic blood transfusion also promotes invasion of cancer cells through IL-6, VEGF and hepatocyte growth factor (HGF)." (PMID 35884557, 2022). "It has been shown that hypoxia activates HGF/c-Met signaling in a hypoxia-inducible factor-1 (HIF-1) dependent manner, leading to the invasive growth of cancer cells through activating the PI3K/Akt pathway." (PMID 35784290, 2022). "Various growth factors, including hepatocyte growth factor (HGF), are known to promote cancer invasion and metastasis, but the regulatory mechanisms involved are not fully understood." (PMID 35085554, 2022). "Consequently, cancer patients might benefit from approaches targeting HGF/c-Met and EpCAM." (PMID 35986321, 2022). "The cancer cell invasion index and DRG axon growth index were suppressed in the HGF + sh mTOR group compared with the HGF group." (PMID 35449152, 2022). "It has been reported that CDCP1 is crucial for the activation of RAS in cancer, and participates in multiple oncogenic pathways, such as EGF signaling and HGF signaling." (PMID 36090897, 2022). "When the HGF/MET pathway is dysregulated, it participates in mediating proliferation, apoptosis, and migration, and induces a variety of cancers." (PMID 35664309, 2022). "Shear stress in the presence of HGF resulted in a concerted effect via a specific c-Met/PI3K/Akt signaling axis through a positive feedback loop, thereby driving cancer stemness and drug resistance." (PMID 35676254, 2022). "LC3C-mediated autophagy was found to selectively regulate the HGF/HGFR-stimulated migration and invasion in HeLa cancer cells." (PMID 35551547, 2022). "HGF and MET are aberrantly upregulated in various cancers, such as breast and esophageal cancers, hepatocellular carcinoma, and non–small cell lung cancer." (PMID 35085554, 2022). "As expected, Hepatocyte Growth Factor (HGF) and Estrogen (E2) significantly increased cancer cell proliferation for, respectively, DU145 and MCF7." (PMID 35887249, 2022). "Hepatocyte growth factor (HGF) is the ligand for c-Met and is responsible for cancer cell proliferation, growth, motility, and migration." (PMID 36428575, 2022). "High lactate levels induce CAFs to overexpress HGF in an NF-κB-dependent manner, which binds to and activates MET on cancer cells, and leads to gefitinib resistance in NSCLC." (PMID 36115852, 2022). "In the cancer cell-DRG coculture system, the cancer cell invasion index and DRG axon growth index, which were inhibited by knockdown of mTOR expression, were recovered by HGF." (PMID 35449152, 2022). "HGF has been reported to enhance the expression of glucose transporters GLUT-1 and GLUT-4 in several types of cancers." (PMID 35081970, 2022). "Recently, a number of agents that target the HGF/c-MET pathway have been developed and evaluated in preclinical and clinical studies of various cancers." (PMID 36034555, 2022). "The MET receptor has thus emerged as a druggable target across several human cancers and agents targeting MET and HGF, including small molecules such as crizotinib, tivantinib, and cabozantinib, have shown therapeutic effects in different tumors." (PMID 35480115, 2022). "MET is a receptor tyrosine kinase also known as the hepatocyte growth factor (HGF) receptor and is directly involved in the invasive growth of cancer cells." (PMID 35495117, 2022). "They recently found that the inhibition of hepatocyte growth factor (HGF)/c-MET pathway, which is upregulated in PC and mediates the interaction between cancer cells and stromal PSCs, can limit primary tumor growth and eliminate metastasis." (PMID 35719926, 2022). "Therefore, the c-MET/HGF axis could be a potential target for cancer therapy." (PMID 36233320, 2022).